YDJC (YdjC chitooligosaccharide deacetylase homolog)
Description:
Probably catalyzes the deacetylation of acetylated carbohydrates an important step in the degradation of oligosaccharides.
Tractability: PROTAC: ubiquitination databases record sites on it.
Gene: Protein-coding gene on chromosome 22 (21,628,089 to 21,630,064, reverse strand). Ensembl gene ENSG00000161179.
Subcellular location (Human Protein Atlas): Golgi apparatus; Vesicles; Cytosol
Gene Ontology:
Molecular function: deacetylase activity; magnesium ion binding
Biological process: carbohydrate metabolic process
Genetic constraint (gnomAD): Loss-of-function variants: 24 observed, 15.52 expected, observed/expected ratio (o/e) 1.55, 90% interval 1.1 to 1.93. The synonymous counts are far from expectation, so gnomAD's model fits this gene poorly and the ratio says little. Missense variants: 467 observed, 391.37 expected, observed/expected ratio (o/e) 1.19, 90% interval 1.11 to 1.29. Synonymous variants: 224 observed, 181.82 expected, observed/expected ratio (o/e) 1.23, 90% interval 1.1 to 1.38.
Homologues: Orthologues: chimpanzee YDJC (99% identical), dog YDJC (87% identical), pig YDJC (87% identical), mouse Ydjc (86% identical), rat Ydjc (85% identical), guinea pig YDJC (81% identical), rabbit YDJC (80% identical), macaque YDJC (65% identical), tropical clawed frog ydjc (46% identical), zebrafish ydjc (46% identical).
Diseases named in the same sentence as YDJC in open-access papers:
YDJC is named in the same sentence as 5 diseases in open-access papers, as found by Europe PMC text mining. Sharing a sentence is not in itself a finding about the gene and the disease. The quoted sentences say what the papers report.
breast carcinoma (2 papers, 2018 to 2020). "CDC16 has been reported as a binding partner of chitooligosaccharide deacetylase homolog (YDJC) in breast cancer cells." (PMID 33051402, 2020). "Furthermore, CDC16 has been proposed as a binding partner of YDJC in breast cancer cells." (PMID 29796162, 2018).
bipolar disorder (1 paper, 2023). A disorder of the brain that causes unusual shifts in mood, energy, activity levels and the ability to carry out day-to-day tasks. "However, we can identify five top genes at 22q11.2 associated with BMI (YDJC, CCDC116, PPIL2, THAP7, UBE2L3), primarily located outside the canonical CNV region (LCR D-E), three with bipolar disorder (TMEM191B, TUBA8, PPIL2), six with ASD (CLTCL1, AC004471." (PMID 37267418, 2023).
lung carcinoma (1 paper, 2018). "We also found that the overall survival was high in lung cancer patients having low expression level of YDJC (n = 1145, p = 0, HR = 1.59 (1.35–1.88))." (PMID 29796162, 2018). "The collective findings indicate that YDJC is involved in SPC-induced events in A549 lung cancer cells by binding to CDC16." (PMID 29796162, 2018). "The collective results indicate that YDJC is involved in SPC-induced events in A549 lung cancer cells by interacting with CDC16." (PMID 29796162, 2018). "KMPLOT analysis based on public microarray data revealed the poor prognosis of lung cancer patients with high expression of YDJC compared with patients with low expression of YDJC." (PMID 29796162, 2018). "In contrast, overexpression of YDJC induced phosphorylation in A549, H23, and H1703 lung cancer cells and reorganization of K8 in A549 cells were observed even without SPC treatment." (PMID 29796162, 2018). "The observation that lung cancer patients with YDJC high expression showed poor prognosis compared with patients with YDJC low expression group suggested that YDJC may be a good target for the development of anticancer drug for lung cancer." (PMID 29796162, 2018). "In this report, we describe SPC-induced YDJC expression in lung cancer cells." (PMID 29796162, 2018). "Initially, we explored whether YDJC expression is related to lung cancer." (PMID 29796162, 2018). "YDJC overexpression might be involved in the progression of lung cancer." (PMID 29796162, 2018). "Gene silencing of YDJC inhibited SPC-induced phosphorylation of K8 in A549, H23, and H1703 lung cancer cells, and reorganization of K8 in A549 lung cancer cells." (PMID 29796162, 2018). "However, there are no reports on the role of YDJC in carcinogenesis and progression of cancer, especially lung cancer." (PMID 29796162, 2018).
cancer (2 papers, 2018 to 2019). A tumor composed of atypical neoplastic, often pleomorphic cells that invade other tissues. "The genes MSL3L2 or MSL3P1 and YDJC appear to be novel and their functions in cancer are unknown, to the best of our knowledge." (PMID 30809433, 2019). "Overall, the results suggest that YDJC is involved in SPC-induced phosphorylation and reorganization of K8 in A549 cancer cells." (PMID 29796162, 2018).
YDJC also shares sentences with these, for which no sentence is quoted: tumor (2 papers).